RNU6-1223P (RNA, U6 small nuclear 1223, pseudogene)
Gene: Small nuclear RNA gene on chromosome 19 (1,616,492 to 1,616,595, reverse strand). Ensembl gene ENSG00000252933.
Homologues: Orthologues: chimpanzee U6 (100% identical), pig U6 (65% identical), guinea pig U6 (62% identical), mouse Gm54442 (60% identical), mouse Gm54479 (56% identical). Paralogues in human: RNU6-128P (75% identical), RNU6-214P (75% identical), RNU6-333P (75% identical), RNU6-10P (74% identical), RNU6-1316P (74% identical), RNU6-20P (74% identical), RNU6-21P (74% identical), RNU6-25P (74% identical), RNU6-310P (74% identical), RNU6-35P (74% identical), RNU6-46P (74% identical), RNU6-574P (74% identical), and 1285 more.